CASR (calcium sensing receptor)
Diseases named in the same sentence as CASR in open-access papers (continued):
Sharing a sentence is not in itself a finding about the gene and the disease.
diabetic nephropathy (2 papers, 2019 to 2020). "Moreover, cinacalcet, a type II agonist of calcium-sensing receptor (CaSR), ameliorated diabetic nephropathy in db/db mice via regulating AMPK/mTOR-mediated autophagy." (PMID 31936109, 2020).
diarrheal disease (2 papers, 2018). The condition of having at least three loose or liquid bowel movements each day. "We also predict that, when this CaSR-mediated anti-secretory protection is decreased or lost, such as in children with a negative calcium balance or nutrient deprivation, this and other diarrheal diseases would be anticipated to be more common." (PMID 29777154, 2018). "However, L-amino acids such as L-Ala, L-Phe, and L-Trp are the agonists of the CaSR; thus they are effective in preventing and treating IBD and other diarrheal diseases via CaSR." (PMID 29682569, 2018).
dyslipidemia (2 papers, 2019 to 2022). "By the Better Associations for Disease and GEnes (BADGE) system, there was the fifth-class association between CASR rs7652589 and dyslipidemia diagnosed by the atherogenic index in the dominant model of inheritance." (PMID 31775661, 2019). "In our study, CASR rs7652589 and rs1801725 correlated with dyslipidemia in HD patients but their simultaneous associations with calcimimetics need to be shown in future studies." (PMID 31775661, 2019). "CASR polymorphisms (rs7652589, rs1801725) are associated with dyslipidemia in HD patients." (PMID 31775661, 2019). "In HD patients, CASR polymorphisms (rs7652589, rs1801725) play a noticeable role in dyslipidemia." (PMID 31775661, 2019). "There is scarce data on CASR associations with dyslipidemia." (PMID 31775661, 2019). "Because CASR rs1801725 SNP is located in exon 7, it probably cannot directly affect the binding of transcription factors involved in dyslipidemia and CAD as it was shown for rs7652589 SNP." (PMID 31775661, 2019). "HD patients harboring the variant allele of CASR rs1801725 revealed about the 1.7-fold lower risk of dyslipidemia diagnosed by non-HDL-cholesterol ≥130 mg/dL and TG ≥ 200 mg/dL compared with homozygotes of the major allele." (PMID 31775661, 2019). "There were associations between CASR SNPs (rs7652589, rs1801725) and dyslipidemia in HD patients not receiving lipid-modifying medications." (PMID 31775661, 2019). "Relative CASR transcript level positively correlates with dry body weight, RXRA, LXRA and ENHO transcripts, and RRT duration, but is not dependent on gender, age, diabetic nephropathy, types of dyslipidemia, or lipid-modifying treatment." (PMID 31775661, 2019). "Dyslipidemia diagnosed by non-HDL-cholesterol ≥130 mg/dL and TG ≥ 200 mg/dL showed an association with BMI (OR 1.12, 95%CI 1.06–1.19, P = 1.7E-4), male gender (OR 0.41, 95%CI 0.24–0.72, P = 0.002), and CASR rs1801725 in dominant model of inheritance (OR 0.52, 95%CI 0.28–0.98, P = 0.042)." (PMID 31775661, 2019). "There were no epistatic interactions between CASR and RXRA, LXRA, and ENHO regarding dyslipidemia." (PMID 31775661, 2019).
esophagitis (2 papers, 2009 to 2024). An acute or chronic inflammatory disease affecting the esophageal wall. "CaSR may play a role in the proliferative response to injury and the pathogenesis of esophagitis." (PMID 38920679, 2024).
female infertility (2 papers, 2016 to 2024). Diminished or absent ability of a female to achieve conception. "Exploration of CaSR function in the context of diseases of reproduction such as male and female infertility and early pregnancy loss, PCOS, or gestational diabetes mellitus as well as tumors of reproductive organs may add novel possibilities for diagnosis and treatment." (PMID 27625611, 2016). "It would be interesting for us to further illuminate the deeper mechanism underlying the function of IL6R, CD274 and CASR, and also HA/NA PCOS classification markers on the formation of PCOS and female infertility." (PMID 38347589, 2024). "Also from the knowledge graph, we noticed the important role for our newly discovered HA and NA PCOS functional markers IL6R, CD274 and CASR on female infertility." (PMID 38347589, 2024).
glioma (2 papers, 2016 to 2024). A benign or malignant brain and spinal cord tumor that arises from glial cells (astrocytes, oligodendrocytes, ependymal cells). "Gene set enrichment analysis showed that CASR was associated with cell adhesion molecules and lysosomes in glioma." (PMID 38509759, 2024). "NPS‐2143, an antagonist of calcium‐sensing receptor (CASR), was selected for further study due to its potent cytotoxicity to glioma cells." (PMID 38509759, 2024). "Our results indicated that the overall survival of glioma patients was negatively correlated with the expression of CASR levels." (PMID 38509759, 2024). "Bioinformatic analysis showed that the prognosis of glioma patients with low expression of CASR mRNA was better than those with high expression of CASR mRNA." (PMID 38509759, 2024). "We found that the overall survival (OS) of glioma patients with a high expression level of CASR was significantly longer than that with a low level of CASR." (PMID 38509759, 2024). "In addition, GSEA revealed that cell adhesion molecules and lysosomes were remarkably enriched in the low‐grade glioma and glioblastoma samples with higher CASR levels, respectively." (PMID 38509759, 2024). "In this study, we found that NPS‐2143, a calcium‐sensing receptor (CASR) antagonist, could inhibit the proliferation of glioma cells and induce cell cycle arrest and apoptosis by suppressing autophagy through mediating the AKT–mTOR pathway." (PMID 38509759, 2024). "Using the online GEPIA platform, we further explore the potential bio‐functions of CASR in glioma." (PMID 38509759, 2024). "Therefore, we speculated that NPS‐2143, the selective CASR antagonist, also might exert anti‐glioma ability by suppressing autophagy." (PMID 38509759, 2024). "Therefore, we further investigated the role of CASR in glioma progression by using bioinformatics." (PMID 38509759, 2024). "In addition, our results showed that the level of CASR mRNA was significantly positively correlated with the signalling pathways of cell adhesion molecules and lysosomes in low‐grade glioma and glioblastoma by using GSEA, which was similar to our previous results." (PMID 38509759, 2024). "The measurements of the T1 values demonstrated a clear involvement of the CaSR in the efflux pathways of Mn2+ ions from the metastatic cells, but not in the glioma cells." (PMID 27995976, 2016). "However, we found no apparent association observed between the expression of CASR and recurrence‐free survival (RFS) in glioma patients." (PMID 38509759, 2024).
Glucose intolerance (2 papers, 2017 to 2025). Glucose intolerance (GI) can be defined as dysglycemia that comprises both prediabetes and diabetes. "Oral administration of a CaSR antagonist compound, known as a calcilytic, rectified the glucose intolerance and hypoinsulinemia of CasrNuf/+ mice and ameliorated glucose intolerance in CasrNuf/Nuf mice." (PMID 28575322, 2017). "Knockdown of CaSR in adult mice specifically in the hypothalamic arcuate nucleus, where GHRH, POMC and AgRP neurons reside, also resulted in increased body weight, adiposity, leptin resistance, and glucose intolerance, and reduced bone mass." (PMID 40501942, 2025).
hyperaldosteronism (2 papers, 2014 to 2025). Overproduction of aldosterone by the adrenal glands, which may lead to hypokalemia and/or hypernatremia. "Activation of the calcium-sensing receptor situated on the basolateral membrane of the thick ascending limb (TAL) results in the suppression of tubular transport in this segment and paracellular transport of magnesium, leading to increased renal excretion and subsequent hyperaldosteronism." (PMID 40291321, 2025).
hyperparathyroid-jaw tumor syndrome (2 papers, 2019 to 2026). "Genetically determined forms, including multiple endocrine neoplasia syndromes, hyperparathyroidism-jaw tumor syndrome, and calcium-sensing receptor-related disorders, are often associated with multiglandular disease, earlier onset, and a higher risk of persistence or recurrence." (PMID 41750717, 2026).
idiopathic pulmonary fibrosis (2 papers, 2023 to 2025). Idiopathic pulmonary fibrosis (IPF) is a nonneoplastic pulmonary disease that is characterized by the formation of scar tissue within the lungs in the absence of any known cause. "Lastly, the concomitant increase in the gene transcripts of protease inhibitors, TIMP1, TIMP3, and SERPINE1, suggest that CaSR may facilitate a profibrotic environment promoting a non-degrading collagen-rich ECM, which is a defining feature of human and animal models of lung fibrosis." (PMID 40305220, 2025).
irritable bowel syndrome (2 papers, 2015 to 2016). Irritable bowel syndrome (IBS) is a chronic functional condition of the lower gastrointestinal (GI) tract characterized by abdominal pain or discomfort and disordered bowel habit (diarrhea, constipation, or fluctuation between the two). "Considering its normal role in the gut, CaSR may represent an excellent candidate gene to be investigated in the pathophysiology of irritable bowel syndrome (IBS), a common clinical condition characterized by chronic diarrhea and/or constipation, in addition to abdominal pain and cramping." (PMID 27458380, 2016).
juvenile myoclonic epilepsy (2 papers, 2012 to 2024). "Increasingly, molecular genetic studies have identified defects in non-ion channel genes in common IE, such as the calcium sensors EFHC1 in juvenile myoclonic epilepsy (JME) and CASR in idiopathic generalized epilepsy (IGE)." (PMID 23209433, 2012). "In patients with juvenile myoclonic epilepsy, several individual loci are involved, of which GABRA1, GABRD, EFHC1, BRD2, CASR, and ICK with complex inheritance are considered to be the most pathogenic." (PMID 39513854, 2024).
liposarcoma (2 papers, 2019 to 2021). A usually painless malignant tumor that arises from adipose tissue. "Cinacalcet decreased TG content in adipocytes (line LS14 derived from a human metastatic liposarcoma) by 20% through CaSR activation but CaSR stimulation in HepG2 cells exhibited a 19% increased TG content in the presence of oleic acid and elevation in the expression of proinflammatory factors." (PMID 31775661, 2019).
lung squamous cell carcinoma (2 papers, 2017 to 2022). "Interestingly, previous studies reported that expression of the wild type and the activating R990G CaSR mutant in exon 7 of the receptor were both necessary and sufficient to induce humoral hypercalcemia of malignancy in lung squamous cell carcinoma xenograft tumor bearing mice." (PMID 35355564, 2022).
multiple endocrine neoplasia (2 papers, 2025 to 2026). Multiple endocrine neoplasia (MEN) is a group of rare inherited cancer syndromes characterized by the development of two or more endocrine gland tumors, sometimes with tumor development in other tissues or organs. "These abnormalities are often linked to syndromes such as Multiple Endocrine Neoplasia (MEN-1, MEN-2A, MEN-4) or mutations in genes such as CASR, CDKN1A, CDKN1B, CDKN2C, and RET." (PMID 41597072, 2025).
myeloma (2 papers, 2020 to 2021). "Previous studies have shown that high Ca2+o stimulates cell proliferation in osteoblasts, myeloma cells, and vascular smooth muscle cells through CaSR-mediated signaling." (PMID 33396907, 2020). "This is how myeloma cells survive in bone marrow microenvironment, indicating that CaSR, at least in part, might mediate these survival signals to regulate the mitosis of myeloma cells." (PMID 34579758, 2021). "In human myeloma cells, such as U266, IM-9 and RPMI8226 cells, exposure to high Ca2+ concentration augmented cell proliferation through CaSR on their surfaces, and further participate in a vicious cycle by expanding myeloma cell mass in destructive bone lesions." (PMID 34579758, 2021). "However, CaSR activators (such as Ca2+, NPS, R467) did not enhance IL-6 expression in these cells, indicating that CaSR agonists exerting a mitogenic effect on myeloma cells seemed to be independent of IL-6 actions." (PMID 34579758, 2021).
neuroendocrine tumours (2 papers, 2021 to 2025). "The findings shed light on the specific role of CaSR as a tumour suppressor in gastroenteropancreatic neuroendocrine tumours." (PMID 39579056, 2025). "Here, the authors show in two independent cohorts that the calcium‐sensing receptor (CaSR) is down‐regulated in gastroenteropancreatic neuroendocrine tumours and that this reduced expression is likely due to alterations in DNA methylation and chromatin organisation." (PMID 39579056, 2025). "Moreover, they show that transfection of gastroenteropancreatic neuroendocrine tumour cell lines with CaSR decreases cell viability." (PMID 39579056, 2025).
parathyroid disease (2 papers, 2017 to 2022). "It is well established that the CaSR is invariably mutated especially in parathyroid diseases." (PMID 28764683, 2017). "Using NGS, we identified three pathogenic variants in two genes (CDC73 and MEN1), 10 likely pathogenic variants in six genes (CASR, CDC73, LRP5, MEN1, SDHA, and VHL), and 39 non-synonymous VUS variants that could be related to parathyroid disease." (PMID 35586626, 2022).
pituitary tumour (2 papers, 2021). "We, therefore, hypothesised that reducing CaSR expression or signalling by the receptor may be a novel treatment for pituitary tumours." (PMID 34223822, 2021). "Moreover, if existing allosteric modulators of CaSR could reduce AtT20 proliferation, these compounds could be repurposed for use in pituitary tumours." (PMID 34223822, 2021). "Thus, reducing CaSR expression may be a viable option in the treatment of pituitary tumours." (PMID 34223822, 2021).
Renal insufficiency (2 papers, 2017 to 2022). A reduction in the level of performance of the kidneys in areas of function comprising the concentration of urine, removal of wastes, the maintenance of electrolyte balance, homeostasis of blood pressure, and calcium metabolism. "For example, treatment for 2 weeks with AMG641, a calcimimetic compound more potent than cinacalcet, upregulated the expression of both CaSR and VDR in rats with renal insufficiency to the similar levels of control." (PMID 34787825, 2022).
salivary gland stones (2 papers, 2020 to 2023). "To further establish the role of TRPC3 in sialolithiasis, we compared the presence of CaSR and TRPC3 in human (non-stone) control and stone patient SMG tissue sections." (PMID 37031239, 2023).
Secretory diarrhea (2 papers, 2016 to 2021). Watery voluminous diarrhea resulting from an imbalance between ion and water secretion and absorption. "A proposed target for treatment of secretory diarrheas is the extracellular calcium-sensing receptor (CaSR)." (PMID 33400691, 2021).
skin cancer (2 papers, 2021 to 2023). "In summary, this study provides robust population-level genetic evidence supporting the notion that expression of the inactivating CaSR rs1801725 SNP predisposes breast, prostate, and skin cancer patients to secondary neoplastic lesions in the lung and bone tissues." (PMID 34357109, 2021). "We previously reported that knockdown of the CaSR or treatment with its negative allosteric modulator, NPS-2143, significantly reduced UV-induced DNA damage, a key factor in skin cancer development." (PMID 36902353, 2023).
spinal cord ischemia (2 papers, 2019 to 2022). Reduced blood flow to the spinal cord which is supplied by the anterior spinal artery and the paired posterior spinal arteries. "The calcium-sensing receptor (CaSR) has been found after spinal cord ischemia-reperfusion injury." (PMID 31998134, 2019).
subarachnoid hemorrhage (2 papers, 2020 to 2022). A serious neurological disorder characterized by intracranial hemorrhage into the subarachnoid space. "In a mouse model of subarachnoid hemorrhage, GdCl3 worsened the brain edema, the extent of neurodegeneration, and the intensity of neurological deficits, whereas the administration of NPS 2143, a CaSR NAM, remarkably reduced all such injuries and deficits." (PMID 33261147, 2020).
type 1 diabetes (2 papers, 2010 to 2020). "Our data evidenced that STZ-induced type 1 diabetes increased oxidative stress, depressed BAG3, Bcl-2, CaSR and p-eNOS expression and evoked vascular dysfunction in vasoconstriction and vasodilation of the mesenteric arterioles." (PMID 32751309, 2020).
acute kidney injury (1 paper, 2021). Sudden and sustained deterioration of the kidney function characterized by decreased glomerular filtration rate, increased serum creatinine or oliguria. "However, the activation of CaSR by L-ornithine can protect from H2O2-induced necrosis in proximal tubular cells and reduce subsequent acute kidney injury (AKI), which is mediated by transient receptor potential canonical (TRPC)-dependent receptor-operated Ca2+ entry." (PMID 34831428, 2021).
aging (1 paper, 2023). A developmental process that is a deterioration and loss of function over time. "Another pathway that has recently been shown to be altered with skin aging is activation of the keratinocyte calcium-sensing receptor (CaSR)." (PMID 37997995, 2023).
Arthritis (1 paper, 2020). Inflammation of a joint. "Allosteric enhancement of CaSR signaling in vivo leads to aggravation of arthritis, which emphasizes the pivotal role of the receptor in this disease." (PMID 32843625, 2020).
autosomal recessive polycystic kidney disease (1 paper, 2018). An inherited disorder characterized by the development of cysts affecting the collecting ducts. "In contrast, another study evaluating the effect of CaSR activation with NPS-R568 in animal models orthologous to human ADPKD and/or ARPKD (Autosomal Recessive Polycystic Kidney Disease), reported no detectable effect on cystogenesis but possible beneficial effect on interstitial fibrosis." (PMID 29632324, 2018).
benign parathyroid tumors (1 paper, 2021). "Decreased CASR transcript expression, but not loss-of-heterozygosity at the CASR chromosomal locus, has been demonstrated in benign parathyroid tumors." (PMID 33716975, 2021).
bladder disorders (1 paper, 2021). "This study provided further evidence of how the urothelial CaSR mediated micturition and implicated the urothelial CaSR as a potential pharmacotherapeutic target in the intervention of bladder disorders." (PMID 34681183, 2021). "We characterized the role of the CaSR in bladder urothelium, elucidated the modulation of micturition function via the urothelial CaSR, and implicated urothelial CaSR as a potential pharmacological target in the treatment of bladder disorders." (PMID 34681183, 2021). "Intravesical administration with CaSR agonist ameliorated cystitis-induced bladder hyperactivity, which further suggested the promising potential of the urothelial CaSR as a pharmacotherapeutic target for bladder disorders." (PMID 34681183, 2021).
brain hemorrhage (1 paper, 2022). "The CaSR was additionally found to mediate a pro-inflammatory stimulus after tissue damage, as observed in a mouse model of brain hemorrhage, where CaSR expression was up-regulated after injury, and its stimulation with Gd3+ increased NLRP3 and IL-1β expression." (PMID 36467702, 2022).